ARSL (arylsulfatase L)
Description:
Exhibits arylsulfatase activity towards the artificial substrate 4-methylumbelliferyl sulfate. May be essential for the correct composition of cartilage and bone matrix during development. Has no activity toward steroid sulfates.
Synonyms: ASE; ARSE; CDPX; CDPX1; CDPXR
Tractability: Antibody: UniProt predicts a signal peptide or a membrane-spanning region.
Gene: Protein-coding gene on chromosome X (2,934,045 to 2,968,475, reverse strand). Ensembl gene ENSG00000157399.
Subcellular location: Golgi apparatus, Golgi stack
Subcellular location (Human Protein Atlas): Golgi apparatus
Pathways (Reactome):
Metabolism: Glycosphingolipid catabolism
Metabolism of proteins: The activation of arylsulfatases
Gene Ontology:
Molecular function: arylsulfatase activity
Biological process: skeletal system development
Cellular component: extracellular exosome; Golgi apparatus; endoplasmic reticulum lumen; Golgi stack
Gene-disease validity (ClinGen):
ClinGen rates the evidence that ARSL causes each of these diseases.
X-linked chondrodysplasia punctata 1 (X-linked): Definitive.
Homologues: Orthologues: macaque ARSL (94% identical), pig ARSE (77% identical), rat Arsl (57% identical), rabbit ARSL (57% identical), Caenorhabditis elegans sul-2 (25% identical), Drosophila melanogaster CG32191 (24% identical), zebrafish arsib (23% identical), Drosophila melanogaster CG7408 (23% identical), Drosophila melanogaster CG7402 (22% identical), Caenorhabditis elegans sul-3 (21% identical), Drosophila melanogaster Sulf1 (19% identical), zebrafish sulf2a (19% identical), and 4 more. Paralogues in human: ARSD (62% identical), ARSH (57% identical), ARSF (56% identical), STS (51% identical), GALNS (30% identical), ARSA (28% identical), ARSG (28% identical), ARSI (26% identical), ARSB (24% identical), ARSJ (23% identical), SGSH (22% identical), SULF2 (21% identical), and 4 more.
Diseases named in the same sentence as ARSL in open-access papers:
ARSL is named in the same sentence as 24 diseases in open-access papers, as found by Europe PMC text mining. Sharing a sentence is not in itself a finding about the gene and the disease. The quoted sentences say what the papers report.
chondrodysplasia punctata (6 papers, 2020 to 2025). A rare congenital developmental disorder characterized by the presence of stippled foci of calcification in the hyaline cartilage, joint contractions, mental retardation and ichthyosis. "Specifically, the duplication crosses a gene (ARSL) associated with chondrodysplasia punctata 1, X-linked recessive (CDPX1)." (PMID 41362902, 2025).
ARSL also shares sentences with these, for which no sentence is quoted: X-linked chondrodysplasia punctata (4 papers); brachytelephalangic chondrodysplasia punctata (3); genetic diseases (2); ichthyosis (2); Intellectual disability (2); Leri-Weill dyschondrosteosis (2); skeletal dysplasia (2); autism (1); cancer (1); cataract (1); cervical spinal stenosis (1); chondrodysplasia (1); craniosynostosis (1); diabetes (1); Keutel syndrome (1); lung carcinoma (1); metachromatic leukodystrophy (1); microcephaly (1); Myelopathy (1); paroxysmal non-kinesigenic dyskinesia (1); tumor (1); Turner syndrome (1); X-linked disease (1).